KIT (KIT proto-oncogene, receptor tyrosine kinase)
Diseases named in the same sentence as KIT in open-access papers (continued):
Sharing a sentence is not in itself a finding about the gene and the disease.
gastrointestinal stromal tumor (continued). "Similarly, PDGFR and KIT, the inhibitors whereof are more effective in gastrointestinal stromal tumors (GIST), are frequently characterized by activating mutations in intracellular domains." (PMID 35158868, 2022). "A broad variety of neoplasms, such as gastrointestinal stromal tumors (GIST), acute myeloid leukemia (AML), mastocytosis, germinomas and melanomas have been shown to be induced by mutations in the KIT gene." (PMID 36028522, 2022). "Somatic mutations of KIT are frequently found in mastocytosis and gastrointestinal stromal tumor (GIST), while germline mutations of KIT are rare, and only found in few cases of familial GIST and mastocytosis." (PMID 35320498, 2022). "Imatinib blocks the receptor tyrosine kinase activity of c-KIT and is a first-line therapy for gastrointestinal stromal tumours (GIST)." (PMID 36232957, 2022). "In conclusion, this study provides evidence for the presence of c-KIT and PDGFRA mutations in canine gastrointestinal stromal tumors and suggests a potential association of c-KIT mutation with the more aggressive biological behavior of the tumor." (PMID 35878393, 2022). "A similar effect is observed in gastrointestinal stromal tumors where hypermethylation of CTCF motifs within the CBS at domain boundaries at KIT and FGF4 loci favours their expression." (PMID 35993175, 2022). "The aim of this study is to investigate the mutational status of c-KIT and PDGFRA, by PCR and sequencing, in 17 canine gastrointestinal stromal tumors." (PMID 35878393, 2022). "Imatinib is a multikinase inhibitor targeting PDGFR, ABL, c-KIT, that is already used for the treatment of gastrointestinal stromal tumor (GIST), and different types of leukemias." (PMID 36408180, 2022). "In other cases, such as gastrointestinal stromal tumors (GIST), the identification of driver mutations in KIT and PDGFRα have effectively realized tailored therapies which radically changed tumor history." (PMID 34068344, 2021). "Its activation is oncogenic in gastrointestinal stromal tumors, melanomas, and lung cancer, and several therapeutics targeting activated KIT have so far been employed." (PMID 34572789, 2021). "Targeting the WEE1 kinase was reported to strengthen the antitumor activity of imatinib via promoting KIT autophagic degradation in gastrointestinal stromal tumors." (PMID 33516270, 2021). "c-KIT is thought to be involved in tumor pathogenesis, including hematologic neoplasia, gastrointestinal stromal tumors, mastocytosis, seminoma, sarcoma, among others." (PMID 34439864, 2021). "Its activation is oncogenic in acute myeloid leukemia, gastrointestinal stromal tumors, melanomas, and lung cancer, and several therapeutics targeting activated KIT have been employed so far." (PMID 34572789, 2021). "Gastrointestinal stromal tumor (GIST) is the most common type of gastrointestinal mesenchymal tumor, primarily harboring gain of function mutations in the KIT or platelet-derived growth factor receptor-alpha (PDGFRA) genes." (PMID 34638938, 2021). "For example, the SNP in the KIT 3′UTR disrupts a miR-221/222 binding site in gastrointestinal stromal tumors." (PMID 33505778, 2021). "In gastrointestinal stromal tumors (GIST), mutations of exons 9, 11, 13 and 17 of KIT, and of exons 12, 14 and 18 of PDGFRA are key drivers of oncogenesis and are present in around 85–90% of tumors, whereas the remaining 10–15% of these cancers is referred as KIT/PDGFRA wild-type GISTs." (PMID 34638228, 2021). "In the study of gastrointestinal stromal tumors, miR-124-3p reduced the viability of tumor cells by inhibiting KIT expression and induced tumor cell apoptosis." (PMID 34582363, 2021). "Several RTKs are clear examples of this context dependence: gastrointestinal stromal tumor mutations prefer IDR mutations in both KIT and PDGFRA, while leukaemia prefers catalytic site mutations in KIT." (PMID 33806614, 2021).
gastrointestinal stromal tumor (continued). "Imatinib is a selective inhibitor of certain tyrosine kinases and is highly active in patients with gastrointestinal stromal tumors (GISTs) by blocking the constitutive activity of KIT and platelet-derived growth factor receptor α (PDGFR-α)." (PMID 33801049, 2021). "Imatinib is a tyrosine kinase inhibitor that specifically targets the kinase activity of PDGFRβ, ABL, and c-KIT and has been approved for the treatment of chronic myeloid leukemia and gastrointestinal stromal tumors (20, –, 24)." (PMID 33753340, 2021). "Succinate dehydrogenase deficient gastrointestinal stromal tumors (SDH-deficient GISTs), which lack KIT or PDGFRA mutations demonstrate unique clinical and pathological features, and they respond poorly to standard targeted therapy." (PMID 33612108, 2021). "Gastrointestinal stromal tumors (GIST) is the most common mesenchymal tumor in the gastrointestinal tract, which is often caused by the mutation of KIT and PDGFRA genes." (PMID 34778339, 2021). "Subsequently, this approval was extended to gastrointestinal stromal tumors (GISTs) that express the receptor tyrosine kinase KIT (tyrosine protein kinase Kit)." (PMID 34461089, 2021). "IMA, a protein tyrosine kinase Bcr-Abl and c-KIT selective inhibitor, is used for the treatment of gastrointestinal stromal tumors and chronic myeloid leukemia." (PMID 32521723, 2020). "MEK and KIT inhibitors impede gastrointestinal stromal tumor (GIST) growth by interrupting the KIT–ETV1-positive feedback circuit in GIST." (PMID 33585247, 2020). "Gastrointestinal stromal tumours result from the deregulated proliferation of transformed KIT‐positive ICCs that share mesenchymal progenitors with SMCs." (PMID 32633461, 2020). "Variant rs55986963 in the KIT gene, according to the NCBI ClinVar database, is associated with gastrointestinal stromal tumors (GISTs), mastocytosis, and partial albinism." (PMID 32708070, 2020). "Considering the efficacy of targeted therapy in KIT-addicted tumors, such as gastrointestinal stromal tumors (GISTs), different prospective studies have evaluated KIT inhibition in melanoma." (PMID 32825562, 2020). "This economic evaluation developed a Markov model to examine the cost-effectiveness of targeted gene testing with tailored imatinib dosing for patients with gastrointestinal stromal tumor based on KIT exon variation status." (PMID 32986105, 2020). "On the other hand, even if leiomyosarcoma and gastrointestinal stromal tumor are correctly diagnosed by KIT staining, there are reports that hepatic metastasis from leiomyosarcoma remains common, and no consensus has been reached." (PMID 32648686, 2020). "Gastrointestinal stromal tumours result from the deregulated proliferation of transformed KIT‐positive cells that originate from mesenchymal progenitors." (PMID 32633461, 2020). "The majority of gastrointestinal stromal tumors (GISTs) are driven by oncogenic KIT signaling and can therefore be effectively treated with the tyrosine kinase inhibitor (TKI) imatinib mesylate." (PMID 32198455, 2020). "Sunitinib or Sorafenib is a tyrosine kinase inhibitor molecule that targets KIT and has antiangiogenic effects, which is utilized for the treatment of advanced gastrointestinal stromal tumors in patients who fail Imatinib therapy." (PMID 31145737, 2019). "Pharmacological targeting of KIT in gastrointestinal stromal tumours has dramatically changed the clinical outcome of this disease." (PMID 30792534, 2019). "Gastrointestinal stromal tumors (GISTs) are frequently driven by auto-activated, mutant KIT and have durable response to KIT tyrosine kinase inhibitor." (PMID 31363162, 2019). "Since KIT and PDGFRA mutations are observed in 85% of gastrointestinal stromal tumors (GISTs), it was also tested and approved for GIST treatment." (PMID 31480389, 2019).
gastrointestinal stromal tumor (continued). "With the gastrointestinal tract as the cause, gastrointestinal stromal tumor (GIST) is seen as the very widespread mesenchymal tumor, and most patients with GIST exhibit activation of the KIT and platelet-derived growth factor receptor (PDGFRA) mutations." (PMID 31032364, 2019). "Activating mutations in KIT are responsible for most of the gastro-intestinal stromal tumors (GIST) and many of the current therapies that target KIT and PDGFRA proteins result in the onset of resistance." (PMID 30682828, 2019). "Mutations within ECD of other RTKs have also been reported, including RET in thyroid cancer and KIT in gastrointestinal stromal tumor (GIST)." (PMID 29455648, 2018). "Gain-of-function mutations in c-KIT gene altered the hyperactivation of RTK and are associated with several human malignancies, such as gastrointestinal stromal tumors (GISTs), acute myeloid leukemia (AML), mast cell leukemia (MCL) and melanoma." (PMID 30404198, 2018). "Active KIT mutations other than KITD816V are generally found in gastrointestinal stromal tumors (GISTs), and so the purpose of this study was to analyze the role of SH3BP2 in other KIT oncogenic mutations associated with pathology." (PMID 29885053, 2018). "In gastrointestinal stromal tumors (GIST), the KIT mutation is an independent risk factor for OS and DFS; this relationship is so important that exon 11 is related to a better therapeutic response." (PMID 29796159, 2018). "Recent advances in molecular biology have revolutionized the concept of KIT/PDGFRA wild type (WT) gastrointestinal stromal tumors (GIST) than the past." (PMID 28535771, 2017). "Imatinib mesylate is a small-molecule inhibitor of the KIT tyrosine kinase, often found in gastrointestinal stromal tumors (GISTs) and melanoma tumors (including mucosal, acral, and those arising from chronically sun damaged skin)." (PMID 28428884, 2017). "Comparable activating mutations occur at the equivalent position in the kinase domain of c-KIT (D816V) in gastrointestinal stromal tumours (GIST) and acute myeloid leukaemia (AML), and in the kinase domain of FLT3 (D835Y) in AML." (PMID 28423505, 2017). "KIT, PDGFRA, NF1 and SDH mutations are alternate initiating events, fostering hyperplasia in gastrointestinal stromal tumours (GISTs), and additional genetic alterations are required for progression to malignancy." (PMID 28270683, 2017). "Gastrointestinal stromal tumors (GISTs) with KIT or platelet-derived growth factor receptor alpha (PDGFRa) oncogenic driver gene mutations, respond to tyrosine kinase inhibitors (TKIs) including imatinib, sunitinib, and regorafenib." (PMID 29100343, 2017). "In addition, imatinib was also used clinically to treat chronic granulocytic leukemia and gastrointestinal stromal tumor (GIST) patients carrying mutations in the gene encoding platelet derived growth factor receptor A (PDGF-RA) or oncogene KIT." (PMID 28813639, 2017). "For example, exosomes derived from gastrointestinal stromal tumor (GIST) cells are enriched with oncogenic protein tyrosine kinase (KIT), are taken up by normal human myometrial smooth muscle cells (SMCs)." (PMID 27941674, 2016). "In the case of KIT, the majority of known somatic mutations were sequenced in AML, melanoma and gastrointestinal stromal tumor (GIST) samples." (PMID 27150584, 2016). "c-KIT is a strong oncogene involved in leukemia, gastrointestinal stromal tumors (GIST) and melanoma, and its inhibition with imatinib has proven to be a highly successful strategy for management of these diseases." (PMID 27533466, 2016). "Distinguishing a leiomyosarcoma from the most commonly encountered mesenchymal gastrointestinal tumor (i.e., the gastrointestinal stromal tumor, GIST, characterized by the presence of activating mutations in KIT or PDGFRA, and expression of CD 117 and/or CD34) is highly important." (PMID 27631424, 2016).
gastrointestinal stromal tumor (continued). "Gastrointestinal stromal tumors (GISTs) originate from the interstitial cells of Cajal (ICC).2 c-KIT (CD117) is a type III receptor tyrosine kinase that is involved in the development and maintenance of ICCs." (PMID 26170517, 2015). "For example, miR-494 inhibits proliferation rate in gastrointestinal stromal tumors cells through directly repression of the KIT." (PMID 26090866, 2015). "Gastrointestinal stromal tumors are characterized by genetic alterations of the activating tyrosine-kinase receptor, KIT (found in 80 % of tumors), and PDGFRA (found in approximately 10 % of tumors)." (PMID 26753123, 2015). "Imatinib (Gleevec), a well-known inhibitor of the oncogenic Bcr-abl fusion protein responsible for chronic myelogenous leukemia (CML), has been used to target PDGFR in gastrointestinal stromal tumors KIT positive." (PMID 26404379, 2015). "It is well known that the KIT oncogene inhibitor imatinib has been widely used in clinical practice and has been approved for use in melanoma, gastrointestinal stromal tumor (GIST), and chronic myelogenous leukemia (CML) patients with KIT mutations." (PMID 25963410, 2015). "AMACR-specific fluorescence in situ hybridization and immunohistochemistry were both informative in tissue microarray sections of 350 independent primary gastrointestinal stromal tumors, including 213 cases with confirmed KIT /PDGFRA genotypes." (PMID 25473890, 2014). "In the past, imatinib mesylate has been successfully used to treat patients with gastrointestinal stromal tumor (GIST), where malignancy is associated with a KIT mutation." (PMID 25609545, 2014). "Targeting KIT with imatinib has demonstrated remarkable efficacy in patients with gastrointestinal stromal tumors (GIST), but initial trials in melanoma were unsuccessful, clearly due to the absence of selection of patients with aberrations in KIT." (PMID 24743024, 2014). "These inhibitors—imatinib, sunitinib, nilotinib, and dasatanib—were developed for different cancers (chronic myeloid leukemia, gastrointestinal stromal tumors) and different kinases, but they showed activity against KIT." (PMID 24743024, 2014). "A recent histo-biochemical study of a small series of SNUC patients showed that these tumours have a strong expression c-KIT, which is a tyrosine kinase receptor typically expressed in gastrointestinal stromal tumours." (PMID 23663264, 2013). "Besides acute leukemia, KIT mutations are found in a large proportion of gastrointestinal stromal tumors (GIST), in subsets of seminomas and melanoma." (PMID 23497317, 2013). "In other cancers including the majority (75-80%) of gastrointestinal stromal tumors (GIST), which originate from cells of the ICC lineage, KIT signaling is constitutively active due to oncogenic mutations." (PMID 24116170, 2013). "Gastrointestinal stromal tumors (GISTs) are almost always positive for CD117 (c-KIT) and very frequently (70%) positive for CD34, whereas gastrointestinal glomus tumors are persistently negative for CD117 and occasionally positive for CD34." (PMID 23691399, 2013). "The benefit that can be derived from accurate characterization of the biology of sarcomas is exemplified by treating gastrointestinal stromal tumors with molecules that inhibit c-KIT and PDGFRA." (PMID 24216705, 2013). "Gastrointestinal stromal tumors or “GIST” are mesenchymal neoplasms expressing KIT(CD117) tyrosine kinase and showing the presence of activating mutations in KIT or PDGFRα (platelet-derived growth factor alpha)." (PMID 23585972, 2013). "Further investigation into the c-KIT gene has been proposed, which would determine response to the imatinib mesylate therapy that is used in other gastrointestinal stromal tumors." (PMID 23841010, 2013). "The discovery and the characterization of KIT/PDGFRA role in GISTs pathogenesis has led to a better identification of GIST among others gastrointestinal stromal tumors and to the development of targeted therapies in this disease." (PMID 23593401, 2013).
gastrointestinal stromal tumor (continued). "Regarding the tumor cells, c-KIT (CD117) is positive in gastrointestinal stromal tumors, but overexpression in several mesenchymal tumors including melanoma, angiosarcoma, and KS was also reported." (PMID 23936513, 2013). "Expression of c-KIT and gain-of-function mutations in c-KIT has been found in mastocytosis, leukemia and gastro-intestinal stromal tumors (GIST)." (PMID 22937135, 2012). "Agents targeting tyrosine kinase activity have an excellent therapeutic index, effectively targeting constitutively activated bcr-abl in CML and KIT in gastrointestinal stromal tumors (GIST), with minimal toxicity compared to cytotoxic therapies." (PMID 23285214, 2012). "The c-KIT is expressed in gastrointestinal stromal tumor (GIST) together with CD34 as double-positive reactivity and therefore must be taken into account in the differential diagnosis." (PMID 22747606, 2012). "Aberrant KIT expression is reported in gastrointestinal stromal tumors (GISTs), acute myeloid leukemia (AML), small cell lung carcinoma, breast cancer, gliomas and neuroendocrine tumors." (PMID 22672386, 2012). "Unprecedented improvement in advanced gastrointestinal stromal tumors (GIST management has been achieved due to recent recognition of the important biological role of activating mutations in KIT and PDGFRA (platelet-derived growth factor receptor- alpha) genes." (PMID 22439647, 2012). "Adjuvant imatinib improves recurrence-free survival of patients following resection of primary KIT-positive gastrointestinal stromal tumors." (PMID 21975443, 2011). "Imatinib mesylate is an effective systemic agent and is indicated in patients with KIT (CD117)-positive gastrointestinal stromal tumors that cannot be surgically removed, and/or have spread to other parts of the body." (PMID 20863383, 2010). "By performing a three-phased internal interlaboratory trial and conducting an external trial in Germany we were able to identify potential pitfalls when performing KIT and PDGFRA mutational analysis in gastrointestinal stromal tumors." (PMID 20598160, 2010). "Mutation analysis of KIT and PDGFRA genes in gastrointestinal stromal tumors is gaining increasing importance for prognosis of GISTs and for prediction of treatment response." (PMID 20598160, 2010). "Constitutively activated KIT would then give rise to the development and/or progression of gastrointestinal stromal tumors in dogs." (PMID 20950418, 2010). "KIT, another RTK, undergoes gain-of-function mutation in >90% of gastrointestinal stromal tumours (GISTs) leading to the activation of PI3K-AKT, mitogen-activated protein kinase (MAPK), STAT-1 and STAT-3 prosurvival pathways." (PMID 19401686, 2009). "Gastrointestinal stromal tumors are KIT-expressing and KIT (tyrosine kinase receptor - CD117)-signaling driven mesenchymal tumors." (PMID 19646278, 2009). "Imatinib is an efficacious drug against chronic myeloid leukemia (CML) and gastrointestinal stromal tumor (GIST) due to selective inhibition of c-KIT and BCR-ABL kinases." (PMID 20523867, 2009). "Mutations in splicing cis-acting sequences have been associated with the BRCA1 gene in breast cancer and the KIT oncogene in gastrointestinal stromal tumor." (PMID 19014521, 2008). "Gastrointestinal stromal tumours typically show expression of CD117/KIT (95%) and frequently CD34 (70%) antigens by immunostaining, yet a small fraction of GISTs lack both diagnostic markers." (PMID 18253129, 2008). "Among the genes involved in signal transduction the KIT gene, one of the main markers of gastrointestinal stromal tumors, showed a high coefficient in this basis experiment." (PMID 16503973, 2006). "This agent, which inhibits BCR-ABL, platelet-derived growth factor receptor (PDGFR) and c-KIT tyrosine kinases, has rapidly become established as the gold standard therapy for chronic myeloid leukaemia and gastrointestinal stromal tumours (GIST)." (PMID 15928655, 2005).